PLEC (plectin)
Diseases named in the same sentence as PLEC in open-access papers (continued):
Sharing a sentence is not in itself a finding about the gene and the disease.
cancer (continued). "Overall, recent strides in understanding plectin’s functional roles in cancer, characterizing its diagnostic and prognostic implications, and realizing its therapeutic potential have generated an exciting momentum towards improving overall survival for many difficult-to-treat cancers." (PMID 34571895, 2021). "Therefore, it is hypothesized that the plectin deficiency-mediated collapse of cytoskeleton may modulate cellular motility that is associated with consequent metastatic behaviors of cancer cells." (PMID 25774093, 2015). "More importantly, plectin in cancer cells often exhibits alterations in subcellular localization, shifting from its typical cytoplasmic distribution to the cell membrane." (PMID 41011568, 2025). "Beyond its structural role in normal tissues, the dysexpression and mislocalization of plectin have been widely acknowledged for their functional relevance in cancer." (PMID 41011568, 2025). "Other known recurrent cancer genes with ≥10 occurrences include PLEC, PDGFRA, NF1, ARID1A, BCOR, and ACVR1." (PMID 41312385, 2025). "In cancer cells, plectin enhances resistance to mechanical stress and is associated with hypoxic conditions." (PMID 41011568, 2025). "We also discuss the novel therapeutic strategies targeting plectin dysregulation to promote precision cancer treatment, including small molecules, mRNA therapies, and antibody therapies." (PMID 41011568, 2025). "By incorporating genes like KASP8 and PLEC, which are crucial in other cancer cell dynamics and chemotherapy responses, the nomogram provides a robust prediction model for treatment outcomes." (PMID 40149716, 2025). "Since then, accumulating evidence has demonstrated that both the expression levels and subcellular localization of plectin are frequently dysregulated in cancer." (PMID 41011568, 2025). "By summarizing these advances, we aim to enhance the understanding of plectin dysregulation in cancer and illuminate its potential as a therapeutic target." (PMID 41011568, 2025). "Among these hallmarks, sustained proliferation is a key feature of cancer progression, in which plectin has emerged as an essential regulator." (PMID 41011568, 2025). "Plectin, a scaffolding protein which bridges cytoskeleton networks, has emerged as a significant driver of malignant hallmarks in various cancers." (PMID 40223002, 2025). "Collectively, these data connect plectin with well-characterized pro-oncogenic signaling pathways which were previously identified as prime candidates for therapeutic intervention in cancer." (PMID 40052672, 2025). "Plectin is frequently upregulated in metastatic tumors, while its downregulation inhibits cancer cell migration through various mechanisms." (PMID 41011568, 2025). "Although plectin is upregulated in most tumor types, its downregulation has also been observed in certain malignancies, indicating a dual expression pattern during cancer progression." (PMID 41011568, 2025). "Here, we focus on recent advances regarding the roles of plectin dysregulation in promoting cell proliferation, suppressing cell apoptosis, sustaining the stemness of cancer stem cells, and driving invasion and metastasis." (PMID 41011568, 2025). "Therapeutic strategies aimed at disrupting plectin dysregulation in cancer have demonstrated potential in suppressing tumorigenesis and progression, including gene knockout, RNA interference-mediated knockdown, and functional inhibition." (PMID 41011568, 2025). "The integration of these discoveries underscores the intricate role of plectin in cancer initiation and progression, which acts as a double-edged sword." (PMID 39334817, 2024). "Multiple studies have suggested that plectin exhibits protumorigenic activities by influencing cancer cell proliferation, migration, and invasion; however, the role of plectin in modulating the tumor immune microenvironment has not been investigated." (PMID 39152432, 2024).
cancer (continued). "The dynamic interplay between plectin and these cytoskeletal components underscores its pivotal role in cancer cells and tumor tissue." (PMID 39334817, 2024). "Here, we first introduce the molecular structure and function of plectin, and then we summarize the current understanding of the crucial role of plectin in cancer progression." (PMID 39334817, 2024). "Pro-tumorigenic participation of plectin was demonstrated in the proliferation, migration, and invasion of these cancers." (PMID 38263015, 2024). "Further analysis of the scRNA-seq and protein databases confirmed that plectin is highly and predominantly expressed by cancer cells in PAAD specimens." (PMID 39152432, 2024). "The review aims to deepen the comprehensive understanding of plectin’s role in cancer and further help to develop novel therapeutic strategies and drug targets." (PMID 39334817, 2024). "In this review, we focus on the crucial role of plectin and provide a deeper understanding of its involvement in cancer progression." (PMID 39334817, 2024). "In the last few years, one of the most exciting advancements in the research on plectin is its emerging role as a potential driving factor in numerous human cancers." (PMID 39334817, 2024). "A high mRNA expression of plectin is significantly correlated with poorer overall survival in several cancers, including PDACs, lung adenocarcinoma, and HNSCC." (PMID 39334817, 2024). "For NECE, five genes were mutated in 80% of patients, including PIK3CA, FAT3, MUC2, PLEC, and TTN, among which PIK3CA and FAT3 belong to the COSMIC Cancer Gene Census gene tier 1 and 2, respectively." (PMID 37920164, 2023). "Owing to its overexpression on the cell membrane and cytoplasm of various tumors, plectin, which is involved in tumor proliferation, migration, and invasion, has been viewed as a promising target for cancer imaging." (PMID 35631582, 2022). "Plectin is upregulated in many cancers and promotes their metastasis; thus, plectin is also used as a biomarker for some cancers." (PMID 36613521, 2022). "Taken together, in cancer cells α6-integrins form adhesions that partially colocalize with plectin and β1-integrin and appear to reside in the proximity of FAs." (PMID 35773413, 2022). "Because the key HD proteins, α6β4-integrins and plectin, play multiple roles in both normal cell differentiation and tumor progression, their use as drug targets in cancer therapy is a very challenging task." (PMID 36612146, 2022). "Plectin overexpression has been identified in a wide range of cancers because of its involvement in various cellular activities in tumors, such as cell proliferation, survival, migration, and invasion." (PMID 35631582, 2022). "Upregulated plectin levels have been correlated with the progression of prostate as well as other cancers." (PMID 35773413, 2022). "Spearman correlation of the 16 hypoxia genes and 151 chemo drugs in the Genomics of Drug Sensitivity in Cancer database revealed that the expression of DCBLD2, PLEC, S100A11, PLAT, PPAP2B and LAMC2 was associated with resistance to most chemotherapies." (PMID 35155430, 2022). "It is also unclear which plectin isoform undergoes this cancer-specific translocation and how this contributes to tumorigenesis." (PMID 36612146, 2022). "Cancer-specific plectin isoform was reported to mitigate drug sensitivity and reduced plectin levels correlated with better efficacy for several drugs such as sorafenib." (PMID 36612146, 2022). "In summary, plectin has been proven to be overexpressed in various tumors, serving as a specific target for cancer diagnosis." (PMID 35631582, 2022). "To obtain quantitative information, we scored all the matched normal vs. cancer samples for staining intensity for plectin, α6-integrin, β4-integrin and PTEN." (PMID 35773413, 2022). "1H11 monoclonal antibody that selectively binds to cancer-specific plectin with a high specificity has been generated." (PMID 36612146, 2022).
cancer (continued). "Recent studies revealing the anticancer effect by directly targeting plectin have opened new avenues of research into plectin’s role in cancer." (PMID 36185199, 2022). "Given the significance of plectin in cytophysiology, its clinical relevance and potential role in cancers deserve to be investigated." (PMID 36613521, 2022). "Multiple studies have emerged implicating plectin as an oncogenic factor due to its involvement in the regulation of the tumorigenic properties of cancer cells." (PMID 36612146, 2022). "Plectin staining was similarly more diffuse in tumor lesions and the staining intensity was particularly high in carcinoma areas devoid of PTEN expression." (PMID 35773413, 2022). "There is evidence that the compartmentalization and control of the actomyosin machinery through plectin-mediated IF network recruitment plays an important role in cancer cell invasion and extravasation for metastasis." (PMID 34440923, 2021). "In fact, plectin has become a paradigm for a protein that, when dysfunctional, causes multisystemic diseases, where different tissues, cell types, and organs, are affected by its dysfunction; an important role of plectin is also emerging in cancer." (PMID 34440923, 2021). "Despite their critical role in driving carcinogenesis, we have a minimal understanding of how aberrant methylation or microRNA (miR) regulation affects plectin expression in cancer." (PMID 34571895, 2021). "The numerous cancer hallmarks impacted by plectin and CSP highlight how the inhibition of one protein can have multifaceted, far-reaching effects." (PMID 34571895, 2021). "We highlight how, beyond their respective biological importance, plectin’s common overexpression in cancer and CSP’s cancer-specific bioavailability underscore their potential as high-value druggable targets." (PMID 34571895, 2021). "Beyond its differential localization, plectin has been widely characterized as commonly overexpressed across multiple cancers, often demonstrating uniquely high expression levels compared to similarly presenting diseases and healthy tissue." (PMID 34571895, 2021). "Evidence shows that beyond plectin’s diverse protein interactome, its cancer-specific mislocalization to the cell surface enables its function as a potent oncoprotein." (PMID 34571895, 2021). "Next, we assessed plectin’s differential gene expression between tumor and healthy tissues across different cancer types using TNMplot." (PMID 34571895, 2021). "As such, therapeutic targeting of plectin, its protein interactors, and, in particular, cancer-specific plectin (CSP) presents an attractive opportunity to impede carcinogenesis directly." (PMID 34571895, 2021). "While pharmacokinetic and pharmacodynamic studies are required to evaluate the clinical translatability of plecstatin-1, its potent anti-cancer effects call attention to the selective targeting of plectin as a robust anti-cancer strategy." (PMID 34571895, 2021). "Plectin’s protumorigenic role and unique cell surface mislocalization in several cancers make it an ideal candidate for targeted imaging and therapeutic strategies." (PMID 34571895, 2021). "Plectin’s stabilization of actin-rich protrusive structures has resulted in plectin being a critical regulator of cancer cell migration and invasion in cancer cells." (PMID 34571895, 2021). "Most notably amongst these is plectin, which was ubiquitously expressed on 100% of cancer tissues analyzed." (PMID 34571866, 2021). "Beyond normal physiology, multiple studies have emerged implicating plectin as a pro-tumorigenic regulator of cancer cell proliferation, migration, and invasion." (PMID 34571895, 2021). "Plectin expression was found to be upregulated in many types of carcinoma cells and tumor tissues, leading to its use as prognostic biomarker and potential therapeutic target." (PMID 34440923, 2021).
cancer (continued). "There are at least 12 known plectin isoforms in humans, and isoforms 1a and 1f have been found on cancer cell surfaces in pancreatic cancer." (PMID 31628412, 2019). "We were able to demonstrate that PCS2 binds to plectin, which normally is expressed intracellularly, but in cancer cells can be expressed on the cell surface." (PMID 31628412, 2019). "In any case, plectin is a highly reliable biomarker and a potential target for various cancer diagnoses and therapies." (PMID 29587367, 2018). "During this cancer preventive process, cytoskeletal proteins plectin and Epithelial Protein Lost In Neoplasm (EPLIN) are accumulated in RasV12 cells that are surrounded by normal cells, which positively regulate the apical elimination of transformed cells." (PMID 29391412, 2018). "Although few studies have demonstrated overexpression in cancer cells, the participation and the mechanisms of action and regulation of plectin in cancer remain elusive." (PMID 29088820, 2017). "Except for 3 pseudogenes (GUCY1B2, HNRNPA1P33, and TUBA3FP), all of the remaining 15 genes showed the most involvement as tumor suppressor genes in distinct carcinomas, and four genes (TUBGCP2, PLEC, CLEC11A, and BARD1) were associated with AML." (PMID 29299160, 2017). "Overexpression of plectin in HNSCC compared to adjacent non-cancerous tissue has been well documented and suggested to promote cancer cell migration and invasion, as suppression of endogenous plectin has been shown to inhibit these processes and downregulate ERK1/2 kinase." (PMID 41009656, 2025). "Collectively, these findings highlight the complex and dual roles of plectin in cancer, indicating that its expression and function may vary among tumor types, stages, and histological subtypes." (PMID 41011568, 2025). "As a pivotal structural protein and cytoskeletal cross-linker, plectin regulates broad cancer cell behaviors, including growth, adhesion, migration, invasion, apoptosis, EMT, pleomorphism, micronucleus formation, and centrosome localization, all crucial for tumor initiation and progression." (PMID 40223002, 2025). "Notably, the form of plectin that is aberrantly localized on the surface of tumor cells and exhibits pro-tumorigenic functions is referred to as cancer-specific plectin (CSP)." (PMID 41011568, 2025). "In recent years, plectin has emerged as a potential oncogenic driver in multiple human cancers." (PMID 40223002, 2025). "Plectin is primarily upregulated in cancer and contributes to tumorigenesis and tumor development." (PMID 41011568, 2025). "Interestingly, emerging evidence in recent years has revealed the dysregulation of plectin in cancer." (PMID 41011568, 2025). "Aberrant plectin expression has often been found across multiple cancer types." (PMID 40223002, 2025). "Interestingly, plectin dysregulation in cancer, characterized by aberrant expression and mislocalization, has been increasingly observed, suggesting distinct roles in tumorigenesis and progression." (PMID 41011568, 2025). "However, accumulating evidence suggests that plectin frequently translocates to the plasma membrane in cancer cells." (PMID 41011568, 2025). "Beyond these cancer types, aberrant plectin expression is observed in other malignancies." (PMID 41011568, 2025). "Secondly, plectin contributes to resistance to apoptosis in cancer." (PMID 41011568, 2025). "Thus plectin has emerged as a biomarker for a number of cancers and it became a candidate for targeting therapies in multiple malignancies." (PMID 38263015, 2024). "Studies have indicated that plakins, including plectin, periplakin, and desmoplakin, could serve as valuable biomarkers in cancer contexts." (PMID 39052015, 2024). "Considering the dual role of integrin α6β4 in cancer progression and its interaction with plectin, we speculate that the dual functionality of plectin may stem from the association between them." (PMID 39334817, 2024).
cancer (continued). "Plectin knockdown inhibits cancer cell growth, colony formation, and xenograft growth." (PMID 39334817, 2024). "The interaction between plectin and breast cancer susceptibility gene 2 (BRCA2) affects centrosome localization, and correct localization plays a significant role in preventing genomic instability and cancer development." (PMID 39334817, 2024). "Further investigation into the precise functions and mechanisms of plectin across various cancers is essential for deepening our comprehension and may lead to the identification of novel therapeutic targets." (PMID 39334817, 2024). "In cancerous tissues, there are significant differences in the expression levels of plectin isoforms, which may play a role in the development and progression of cancer." (PMID 39334817, 2024). "In several types of cancer plectin is upregulated and its intracellular localization is altered." (PMID 38263015, 2024). "Therefore, in-depth exploration of the role and regulatory mechanisms of plectin in cancer is of paramount significance." (PMID 39334817, 2024). "In light of plectin’s emerging role as a potential biomarker and therapeutic target, based on its cell surface localization in several cancers, we investigated whether plectin should also be considered as a biomarker of GBM." (PMID 38263015, 2024). "Abnormal expression of plectin has often been found in various tumor types The coordination of the cytoskeletal network and its dynamics is a fundamental characteristic of cell migration and cancer cell invasion." (PMID 39334817, 2024). "In summary, the dual effects of plectin in tumor progression may be subject to the integrated regulation of various factors, including cancer type, tissue specificity, and interactions with integrin α6β4." (PMID 39334817, 2024). "In the recent two decades, the general role of plectin in cancer has been recognized." (PMID 39334817, 2024). "Also, in certain types of cancers, the bulk cytoplasmic distribution of plectin is altered, predominantly redistributing toward the plasma membrane." (PMID 38263015, 2024). "Finally, we also discuss the possible reasons for the different roles of plectin expression in various types of cancer and highlight the double-edged sword role of plectin in tumor progression." (PMID 39334817, 2024). "The importance of plectin in cancer cells and tumor tissue has been confirmed in recent years." (PMID 39334817, 2024). "Importantly, plectin expression increased in the luminal-like cancer cells in patients with more advanced diseases." (PMID 35773413, 2022). "α6β4-integrins and plectin play a central role in the progression of several types of cancer." (PMID 36612146, 2022). "Keratins are well-known interacting partners with plectin, which has been reported to bind with integrin α6β4 and act as a dominant driver of malignant tumorigenesis via diverse cellular activities including cancer cell proliferation, migration and invasion." (PMID 35706019, 2022). "However, the oncogenic functions of plectin and α6-integrin upon HD disassembly appear to be consistent in many cancer types." (PMID 36612146, 2022). "Subsequently, plectin was shown to be overexpressed in various tumors, including ovarian, lung, head and neck, esophagus, prostate, and colon tumors, and has been viewed as a promising target for cancer diagnosis and treatment." (PMID 35631582, 2022). "We found that HDs, as depicted by intense α6-integrin, β4-integrin, and plectin signals at the basal membrane of basal epithelial cells, were present only in normal glands whereas in cancer lesions these markers were either lost or presented different a more diffuse staining pattern." (PMID 35773413, 2022). "However, plecstatin-1 targets the scaffold protein plectin and is believed to be an indirect ROS-inducer because the interaction of plecstatin-1 with plectin affects cytoskeletal organisation in cancer cells and impacts on mitochondrial distribution." (PMID 35178376, 2022).